TRIL (TLR4 interactor with leucine rich repeats)
Description:
Component of the TLR4 signaling complex. Mediates the innate immune response to bacterial lipopolysaccharide (LPS) leading to cytokine secretion.
Synonyms: KIAA0644
Tractability: Antibody: UniProt predicts a signal peptide or a membrane-spanning region; its Gene Ontology location is reachable by antibodies, with medium confidence.
Gene: Protein-coding gene on chromosome 7 (28,953,358 to 28,958,330, reverse strand). Ensembl gene ENSG00000255690.
Subcellular location: Membrane
Gene Ontology:
Molecular function: lipopolysaccharide binding; protein binding; signaling receptor activity
Biological process: regulation of cytokine production involved in immune response; toll-like receptor 4 signaling pathway
Cellular component: lipopolysaccharide receptor complex; plasma membrane; membrane
Genetic constraint (gnomAD): Loss-of-function variants: 23 observed, 31.68 expected, observed/expected ratio (o/e) 0.73, 90% interval 0.52 to 1.03. The synonymous counts are far from expectation, so gnomAD's model fits this gene poorly and the ratio says little. Missense variants: 1,114 observed, 985.69 expected, observed/expected ratio (o/e) 1.13, 90% interval 1.08 to 1.19. Synonymous variants: 602 observed, 484.19 expected, observed/expected ratio (o/e) 1.24, 90% interval 1.16 to 1.33.
Homologues: Orthologues: chimpanzee TRIL (99% identical), macaque TRIL (96% identical), dog TRIL (91% identical), guinea pig TRIL (89% identical), rat Tril (89% identical), mouse Tril (88% identical), tropical clawed frog tril (48% identical), zebrafish tril (40% identical), Caenorhabditis elegans sma-10 (15% identical), Drosophila melanogaster kek3 (15% identical), Drosophila melanogaster CG18095 (14% identical), Drosophila melanogaster Con (13% identical), and 3 more. Paralogues in human: CPN2 (21% identical), LRIG1 (21% identical), LRIG2 (20% identical), LRIG3 (19% identical), CHADL (18% identical), LRRC24 (17% identical), LGR5 (17% identical), LGR6 (17% identical), LGR4 (15% identical), LRRTM2 (15% identical), LRRC26 (12% identical), ELFN1 (11% identical), and 10 more.
Diseases named in the same sentence as TRIL in open-access papers:
TRIL is named in the same sentence as 9 diseases in open-access papers, as found by Europe PMC text mining. Sharing a sentence is not in itself a finding about the gene and the disease. The quoted sentences say what the papers report.
brain injury (1 paper, 2022). Acute and chronic (see also brain INJURIES, CHRONIC) injuries to the brain, including the cerebral hemispheres, CEREBELLUM, and brain STEM. "Our findings indicate that TriL is protective in models of I/R-induced brain injury, carotid artery ligation-induced intimal hyperplasia in vivo and PDGF-BB-stimulated VSMC migration in vitro." (PMID 36361610, 2022).
cerebral infarction (1 paper, 2022). An ischemic condition of the brain, producing a persistent focal neurological deficit in the area of distribution of the cerebral arteries. "This present study aimed to evaluate the protective effects of TriL in models of ischemia/reperfusion (I/R)-induced cerebral infarction, carotid artery ligation-induced intimal hyperplasia in vivo, and PDGF-BB-stimulated VSMC migration in vitro." (PMID 36361610, 2022). "TriL treatment (50, 100, and 200 mg/kg, p.o.)significantly reduced cerebral infarction compared with the control group." (PMID 36361610, 2022).
Cerebral ischemia (1 paper, 2022). Restriction of arterial blood supply to the brain associated with insufficient oxygenation to support the metabolic requirements of the tissue. "Accordingly, we investigated the protection of TriL on cerebral ischemia/reperfusion (I/R) and vascular smooth muscle cell (VSMC) migration in vivo and in vitro." (PMID 36361610, 2022). "In this study, TriL dose-dependently ameliorated I/R-induced cerebral injury, including reduced infarct size and functional deficits, and mitigated neuronal apoptosis, revealing the neuroprotective effect of TriL on cerebral ischemia partially via the anti-oxidative and anti-inflammatory effects." (PMID 36361610, 2022). "TriL could be potentially efficacious in preventing cerebral ischemia and cerebrovascular diseases." (PMID 36361610, 2022). "The effects of TriL on cerebrovascular diseases such as cerebral ischemia and carotid stenosis have never been studied." (PMID 36361610, 2022). "However, the protective potential of TriL on cerebrovascular diseases such as cerebral ischemia-induced brain injury has not yet been studied." (PMID 36361610, 2022).
cerebrovascular diseases (1 paper, 2022). "Furthermore, it implies TriL may have therapeutic potential for neuroprotection and treating cerebrovascular diseases." (PMID 36361610, 2022). "In the present study, TriL treatment showed a dose-dependent inhibitory effect on carotid artery ligation-induced intimal hyperplasia and reduced PCNA expression in the neointima, which implies TriL may have therapeutic potential for cerebrovascular diseases." (PMID 36361610, 2022).
hearing loss (1 paper, 2019). "This study is the largest GWAS meta-analysis of ARHI to date and identified 7 associated loci, of which 5 are novel (FXYD5, IPP, SPIRE2, SPTBN1 and TRIL) and 2 have been previously related to hearing loss (ILDR1, ISG20)." (PMID 31645637, 2019).
Niemann-Pick disease, type C1 (1 paper, 2012). Type C Niemann-Pick disease associated with a mutation in the gene NPC1, encoding Niemann-Pick C1 protein. "Three known genes, TLR4 interactor with leucine rich repeats (TRIL), Niemann-Pick disease, type C1, gene-like 1 (NPC1L1), and C4orf7 also termed follicular dendritic cell secreted protein were selected by three of the four methods." (PMID 22606341, 2012).
tumor (1 paper, 2022). "We showed that MLLT11, TRIL, and p-AKTThr308 were significantly expressed in tumor tissues compared with the normal endometrial tissues." (PMID 35253622, 2022).
TRIL also shares sentences with these, for which no sentence is quoted: endometrial cancer (1 paper); injury (1).